FOSB (FosB proto-oncogene, AP-1 transcription factor subunit)
Diseases named in the same sentence as FOSB in open-access papers (continued):
Sharing a sentence is not in itself a finding about the gene and the disease.
osteosarcoma (12 papers, 2010 to 2024). A usually aggressive malignant bone-forming mesenchymal neoplasm, predominantly affecting adolescents and young adults. "While c-Jun, c-Fos and FosB efficiently transform mammalian cells in vitro, only c-Fos overexpression causes osteosarcoma formation, whereas c-Jun is required for development of chemically induced skin and liver tumors in mice." (PMID 26398940, 2015). "In conclusion, immunohistochemistry against FOS/FOSB continues to represent the quickest, most cost-effective and reasonable diagnostic add-on to confirm the diagnosis of osteoblastoma and to exclude (osteoblastoma-like) osteosarcoma." (PMID 35347251, 2022). "Research has shown that the expression of FosB is reduced in osteosarcoma cells compared to normal bone cells." (PMID 38966281, 2024). "FosB is thought to play a role in the development and progression of osteosarcoma by promoting the proliferation and survival of cancer cells." (PMID 38966281, 2024). "The identification of FOS/FOSB overexpression is helpful in routine diagnostics but as outlined is not present in all cases and can be identified also in a small subset of osteosarcomas." (PMID 35347251, 2022). "We also observed downregulation of transcription factors AHR (Aryl Hydrocarbon Receptor), FOSB (FBJ Murine Osteosarcoma Viral Oncogene), and KLF4 (Kruppel-Like Factor)." (PMID 29123522, 2017). "A number of acute or repeated stimuli can induce expression of DeltaFosB (ΔFosB), a transcription factor derived from the fosB gene (an osteosarcoma viral oncogene) via alternative splicing." (PMID 27303299, 2016). "This suggests that FosB may also contribute to the development of osteosarcoma by altering the normal processes of bone formation and remodeling." (PMID 38966281, 2024). "Overall, while the exact role of FosB in osteosarcoma is still being studied, there is evidence to suggest that it may be a potential target for the development of new treatments for this aggressive form of bone cancer." (PMID 38966281, 2024). "Of those 24 upregulated genes, five separate/unique FBJ osteosarcoma viral oncogenes (specifically, FOSB and the truncated splice form Δfosb2) belonging to the eight most highly differentially expressed genes (log fold change = 3.58 to 7.78) were found at t1 for VGII R265 only." (PMID 30355668, 2018). "The osteosarcoma case showed, in addition to multiple copies of the FOS-locus, also multiple copies of the FOSB-locus." (PMID 31768625, 2020). "Two of 21 osteoblastomas were FOSB positive (in addition to FOS), while all 22 osteoid osteomas, all 3 osteoblastoma-like osteosarcomas, and both cases with reactive callus formation were negative." (PMID 31768625, 2020). "This suggests that the approach shown here can indeed help in discriminating osteoblastoma from conventional osteosarcoma even in the absence of a detectable FOS/FOSB fusion, representing a useful complementary tool." (PMID 35347251, 2022). "FOSB rearrangements were absent in 5 cases in which FISH was successful (BPOP (n=1), osteosarcoma (n=1), giant cell tumor of bone (n=2), and osteoblastoma (n=1))." (PMID 31768625, 2020). "Indeed, osteosarcoma can infrequently show nuclear FOS expression and a small fraction of osteoblastomas seem to arise independent of FOS/FOSB rearrangements." (PMID 35347251, 2022).
Anxiety (11 papers, 2013 to 2025). Intense feelings of nervousness, tension, or panic often arise in response to interpersonal stresses. "Consistently, therapeutic administration normalized neural responses, as evidenced by changes in histone H3 acetylation, as well as FosB and c-Fos expression, in key brain regions implicated in anxiety regulation." (PMID 40507117, 2025). "These included histone H3 acetylation and immediate early gene expression (c-Fos, FosB) in key brain regions because changes in the level of these markers have been associated with not only anxiety-like responses but also nociception in the periphery." (PMID 40507117, 2025). "Four weeks of UCMS increased anxiety-like and depressive-like behaviors associated with FosB activation in mPFC PV neurons, particularly in females." (PMID 36808099, 2023). "These behavioral improvements were paralleled by reductions in acetylated histone H3, FosB, and c-Fos expression in key anxiety-related brain regions, suggesting a reversal of craniofacial inflammation-associated neural changes." (PMID 40507117, 2025). "Only a few studies altering a transcription factor, fosB, have indicated a possible link of increased ectopic cells to increased anxiety." (PMID 35875667, 2022). "FosB upregulation in the BLA was also observed in nerve injury mice who exhibited anxiety-like behaviors." (PMID 26747511, 2016). "A recent study identified SRF as a novel upstream mediator of FosB in nucleus accumbens after chronic social defeat stress, and implicated SRF in the development of depressive- and anxiety-like behaviors." (PMID 24124448, 2013). "Because our findings showed that Dsp knockdown in the DG reduced the expression of the neuronal activity marker FosB, the suppression of neuronal activity in the DG by Dsp knockdown may also contribute to anxiety-like behavior." (PMID 39176381, 2024). "Similarly, ΔFosB rescue in FosB KO vHPC-BLA neurons blocked the FosB KO-mediated reduction in basal anxiety and impairment in avoidance learning." (PMID 32901027, 2020). "However, it might be the case that in males, exclusively activating IL, and not PrL, PV+ neurons, is necessary to heighten stress-induced anxiety, as suggested by the PV/FosB data indicating that only IL PV neurons are impacted by 8 weeks of UCMS." (PMID 36808099, 2023). "fosB KO mice showed an increased number of hilar ectopic cells after kainic acid (KA)-induced acute seizures, and manifested increased anxiety, in agreement with our IL-17A data demonstrating that reduced EGC production in IL-17A KO could attenuate epilepsy-associated anxiety." (PMID 35875667, 2022). "Our correlation analyses further supported that anxiety (in MBT) and depression levels (in TST) are inversely correlated with FOSB positivity in ovBNST/CRH cells, in agreement with previous findings in rats." (PMID 36213293, 2022). "Chronic seizures increased anxiety-like behaviors and TRPV1 and FosB expression in limbic and brainstem structures involved with epilepsy and anxiety comorbidity, such as the hippocampus, superior colliculus, and periaqueductal gray matter." (PMID 35203625, 2022). "We also characterized the impact of AK, a model of TLE, on anxiety-like behaviors and TRPV1 and FosB expression in the brainstem and limbic structures involved with the comorbidity epilepsy and anxiety in animals of the WAR strain." (PMID 35203625, 2022). "We also observed stress effects in allodynia and anxiety, but vHPC-NAc FosB KO did not alter these behaviors." (PMID 32901027, 2020). "In the absence of FosB KO, ΔFosB overexpression did not affect basal anxiety or avoidance learning in either projection." (PMID 32901027, 2020). "Moreover, a negative correlation of anxiety level with ovBNST CRH/-FOSB cell count (ρ=-0.54; p<0.001) and with CRH/CeA SSD (ρ=-0.58; p<0.001) was detected." (PMID 36213293, 2022).
Anxiety (continued). "Accordingly, taking into account that both FosB labeling and functional inactivation approaches were assessed in the structure as a whole, the present results did not clarify the involvement of the amygdala in the anxiety response induced by emotional contagion." (PMID 36688134, 2022).
lung carcinoma (10 papers, 2014 to 2025). "The role of FOSB in the progression and prognosis of lung cancer seems extremely challenging to follow." (PMID 39164746, 2024). "The overexpression of FosB gene attenuated lung cancer growth and induced the death of the cancer cells." (PMID 38966281, 2024). "The high expression of KRT6A protein is related to good prognosis in patients with lung adenocarcinoma; FOSB protein plays an anti-tumor role in lung cancer." (PMID 36817446, 2023). "In contrast, for the genes LUM and FOSB, lower expression in lung cancer patients denote poor survival." (PMID 35406434, 2022). "In the case of FOSB, the plasma showed a variation from the tissue biopsy, whereby the relative expression of this gene was higher in lung cancer patients than in asthmatics." (PMID 35406434, 2022). "Further investigation using the Kaplan–Meier plotter revealed that the high expression levels of two hub genes, FOSB and PECAM1, were associated with a significantly extended first-progression survival (FPS) in lung cancer patients, with hazard ratios (HRs) of 0.63 and 0.56, respectively." (PMID 40361912, 2025). "A recent report found that the reverse expression of SETDB1 and FosB may be the potential pathway of cell proliferation and diffusion in lung cancer." (PMID 34299035, 2021). "Whether FOSB plays the role of a friend or foe in the evolution and prognosis of lung cancer?" (PMID 39164746, 2024). "Analysis of the enriched genes derived from the pathway analysis identified seven genes present in both asthma and lung cancer: BCL3, POSTN, PPARD, STAT1, MYC, CD44, and FOSB." (PMID 35406434, 2022). "The fold changes in gene expression in lung cancer relative to asthmatic cell lines were in line with the in silico prediction for the genes BCL3, CD44, PPARD, POSTN, FOSB, and STAT1." (PMID 35406434, 2022). "Analysis of the enriched genes derived from the pathway analysis identified seven genes expressed in both the asthma and lung cancer sets: BCL3, POSTN, PPARD, STAT1, MYC, CD44, and FOSB." (PMID 35406434, 2022). "A number of established lung cancer oncogenes have also been included in the classifier, such as IL1R2, JUNB, EGFR, SOX9, FOSB, and JUND." (PMID 27935865, 2017). "We obtained five key genes such as GREM1, MMP11, SPP1, FOSB, and IL33 which were strongly associated with lung cancer in nonsmoking women, which improved understanding and could serve as new therapeutic targets, but their functionality needs further experimental verification." (PMID 34671675, 2021). "Moreover, the reverse expression of SETDB1 and FosB mediated by MEK/ERK2 in anticancer drug therapy may be the potential pathway of cell proliferation, migration, transformation capacity, and diffusion in lung cancer." (PMID 34299035, 2021).
vascular tumors (9 papers, 2018 to 2025). "FOSB rearrangements have been described in two different types of vascular tumours, namely pseudomyogenic haemangioendothelioma and epithelioid haemangioma." (PMID 29858576, 2018). "Additionally, gene fusions involving FOS, FOSB, YAP1, and WWTR1 have been discovered in vascular tumors, improving diagnostic accuracy." (PMID 40428263, 2025). "Similar rearrangements of FOS and FOSB were previously found in vascular tumors." (PMID 31768625, 2020). "Fusion transcripts involving the FOSB gene on 19q13 with SERPINE1 (7q22), ACTB (7p22) and WWTR1 (3q25) have been detected and may be useful in the differentiation of PMH from other vascular tumors." (PMID 40277775, 2025). "ALHA is currently considered a vascular neoplasm with known FOS and FOSB gene rearrangements." (PMID 36611215, 2023).
depression (8 papers, 2016 to 2025). "We next sought to determine whether cocaine dependence, untreated depression, or depression coupled with exposure to antidepressant medication are associated with changes in FosB gene products in human HPC or PFC." (PMID 27494187, 2016). "Authors showed that FosB knockout mice exhibit depression and spontaneous epilepsy symptoms with ectopic migration of NPCs and reduced neurogenesis in the hippocampus." (PMID 40519263, 2025). "Previous studies have shown that FOSB is related to human stress and is a potential therapeutic target for depression." (PMID 35910761, 2022). "Our analyses focused on the expression of FosB gene products, as their expression in these regions has been suggested to play a role in depression and is induced by cocaine exposure in rodent models." (PMID 27494187, 2016). "FOSB is also a reliable marker for long-term changes in neuronal activity in depression models." (PMID 36233039, 2022). "This phenomenon may have great translational relevance, as FOSB-related transcriptional changes were suggested to determine therapeutic efficacy in the management of major depression." (PMID 36233039, 2022). "FosB/ΔFosB is a long-half-life transcription factor which accumulates in neurons over days and weeks, and whose expression modulates hippocampal neuron excitability in the context of chronic stress, depression, and addiction and thereby influences the functional phenotype of nearby microglia." (PMID 38878098, 2024). "Notable downregulated genes matching depression were: BDNF, the glucocorticoid receptor, NR3C1, and activity related genes, EGR1, FOS, NR4A1, FOSB, and ARC." (PMID 34997033, 2022). "We therefore examined the expression of FosB gene products, as well as the expression of potential ΔFosB target genes, in the PFC and HPC of patients suffering from major depressive disorder or cocaine addiction." (PMID 27494187, 2016). "On the contrary, as we observe similar decreases in HPC FosB isoform expression with depression and addiction, it is possible that reduction in HPC FosB gene expression is a common mechanism between the two conditions and may contribute to comorbidity." (PMID 27494187, 2016). "In conclusion, we find that multiple FosB gene products are downregulated in the HPC, but not the PFC, of humans suffering from addiction and depression." (PMID 27494187, 2016).
Osteoblastoma (8 papers, 2018 to 2025). A rare benign bone-forming neoplasm usually arising from the spine. "Rearrangements of the transcription factors FOS and FOSB have recently been identified as the genetic driver event underlying osteoid osteoma and osteoblastoma." (PMID 35347251, 2022). "The exact frequency of osteoblastomas with FOS or FOSB mutations varies depending on the methodology applied." (PMID 32542935, 2020). "Extending our findings into a cohort of 55 cases, using FISH and immunohistochemistry, provide evidence of ubiquitous mutation of FOS or FOSB in osteoblastoma and osteoid osteoma." (PMID 29858576, 2018). "Recently, recurrent translocations in FOS and FOSB have been detected in osteoblastoma, as well as osteoid osteoma, and may be of diagnostic value." (PMID 40506925, 2025). "Taken together, our findings indicate that FOS and FOSB alterations may be exploited as diagnostic markers for osteoblastoma and osteoid osteoma." (PMID 29858576, 2018). "Rearrangements in FOS, and less frequently FOSB, have recently been identified in osteoid osteoma and osteoblastoma." (PMID 41424327, 2025). "Although highly desirable, the molecular characterization of osteoblastomas relying on the expression of FOS/FOSB by IHC can be misleading in some cases." (PMID 35347251, 2022). "In the FOSB rearranged osteoblastoma, rearrangement resulted in an in frame fusion connecting PPP1R10 to FOSB, leading to altered signalling, due to promotor swapping." (PMID 31741049, 2020). "Recently, recurrent translocations in FOS (87%) and FOSB (3%) were found in osteoblastoma and osteoid osteoma." (PMID 31768625, 2020). "Osteoblastoma is a bone‐forming tumour that harbours mutations affecting FOS, or more rarely its paralogue FOSB, in a high proportion of cases." (PMID 32542935, 2020). "We compared immunohistochemistry of FOS and FOSB between osteoid osteoma and osteoblastoma and other lesions with bone deposition." (PMID 31768625, 2020). "The discovery of FOS and FOSB rearrangements found in osteoid osteoma and osteoblastoma have not only given insight in tumorigenesis, but have also provided the bone tumour pathologist with a novel diagnostic tool to improve diagnostic accuracy." (PMID 31741049, 2020). "All three samples demonstrated strong nuclear FOS immunoreactivity, supporting the notion that alterations in FOS or FOSB underpin every case of osteoblastoma and osteoid osteoma." (PMID 29858576, 2018). "Here, the authors report rearrangement of FOS and its paralogue FOSB in osteoblastoma and osteoid osteoma, revealing human bone tumours that are defined by mutations of FOS and FOSB." (PMID 29858576, 2018). "Here, we report recurrent rearrangement of FOS and its paralogue, FOSB, in the most common benign tumours of bone, osteoblastoma and osteoid osteoma." (PMID 29858576, 2018). "Our key finding was recurrent, disease-defining structural variation of the FOS and FOSB oncogenes in osteoblastoma and osteoid osteoma." (PMID 29858576, 2018). "At the same time, FOSB is also expressed in epithelioid haemangiomas and in osteoblastomas." (PMID 34514569, 2022). "Novel FOS and FOSB rearrangements were recently found in osteoid osteoma and osteoblastoma." (PMID 31741049, 2020). "Although FOS and FOSB mutations are frequent findings in osteoblastoma, they do not underlie all cases." (PMID 32542935, 2020). "In 2018, in a quiet genomic background with paucity of somatic alterations, recurrent FOS and—to a lesser extent—FOSB rearrangements were found in both osteoid osteoma and osteoblastoma using RNA sequencing, demonstrating that both tumours were similar at the molecular level." (PMID 31741049, 2020). "Whereas immunohistochemistry is not specific for an underlying translocation and can be influenced by tissue preservation, a smaller fraction of osteoblastomas are characterized by homozygous NF2 deletion and lack FOS/FOSB rearrangements." (PMID 35347251, 2022).
Osteoblastoma (continued). "Osteoid osteoma and osteoblastoma are bone-forming tumors shown to harbor FOS (87%) and FOSB (3%) rearrangements." (PMID 31768625, 2020). "To summarize, FOS immunohistochemistry can be used as an auxiliary tool for osteoid osteoma and osteoblastoma in short decalcified tissue, while FOSB immunohistochemistry is diagnostically not useful." (PMID 31768625, 2020). "Notably, five FOS/FOSB-negative osteoblastomas coming from the study of Lyskjaer9 were also properly positioned within the osteoblastoma cluster." (PMID 35347251, 2022). "Moreover, previous studies described osteoblastomas rich in epithelioid appearing cells that did not carry FOS/FOSB gene fusions." (PMID 35347251, 2022). "Two osteoblastomas (5%) were positive for FOSB, as opposed to 8/177 control cases." (PMID 31768625, 2020). "Finally, we could not find similar FOS and FOSB rearrangements in whole-genome sequences in 2652 non-osteoblastoma tumours." (PMID 29858576, 2018).
colorectal cancer (7 papers, 2008 to 2025). A primary or metastatic malignant neoplasm that affects the colon or rectum. "Because overexpression of c-Fos induces apoptosis in human colorectal carcinoma cells, we focused on the c-Fos and FosB genes, which were conspicuously up-regulated in PC-3 and DU-145, but were weakly up-regulated in TIG-1 and even less so in LNCaP (pink and turquoise arrows in S2 Fig)." (PMID 26230090, 2015). "FOSB is increasingly regulated by ATF3 from the healthy adjacent region to the core region, and it plays a critical role in regulating inflammatory molecule expression, which influences the therapeutic effects of drugs on colorectal cancer." (PMID 40585960, 2025). "Interestingly, IL-6 receptor levels have been reported to reflect OSA severity; FOS, FOSB, and JUN have been demonstrated to be involved in obesity, osteoporosis, and colorectal cancer; and DUSP1 is upregulated in CIH in OSA patients." (PMID 36468038, 2022).